Y_RNA (Y RNA )
Gene: Miscellaneous RNA gene on chromosome 12 (104,851,824 to 104,851,918, forward strand). Ensembl gene ENSG00000222579.
Homologues: Orthologues: chimpanzee Y_RNA (98% identical), macaque Y_RNA (81% identical), guinea pig Y_RNA (77% identical). Paralogues in human: RNY4 (83% identical), Y_RNA (83% identical), RNY4P13 (82% identical), RNY4P19 (82% identical), RNY4P6 (82% identical), RNY4P24 (81% identical), Y_RNA (81% identical), RNY4P10 (80% identical), RNY4P20 (80% identical), RNY4P25 (80% identical), RNY4P7 (80% identical), RNY4P14 (79% identical), and 87 more.